FGF21 (fibroblast growth factor 21)
Diseases named in the same sentence as FGF21 in open-access papers (continued):
Sharing a sentence is not in itself a finding about the gene and the disease.
liver fibrosis (continued). "Furthermore, liver collagen deposition, visualized by Picrosirius red staining, was higher in lipodystrophic mice, and this hepatic fibrosis was visually and quantitatively reduced following transduction with FGF21/sTGFBR2 in both genotypes." (PMID 40663389, 2025). "Notably, FGF21 level is known to increase with age, liver fibrosis, and habitual alcohol consumption." (PMID 40563517, 2025). "BDL-induced liver fibrosis in the WT mice was accompanied by high induction of FGF21." (PMID 39040469, 2024). "Compared to the WT mice, the FGF21 KO mice showed more severe liver fibrosis induced by BDL." (PMID 39040469, 2024). "Interestingly, our results revealed that FGF21 overexpression not only reduced liver fibrosis and bile duct proliferation but also expanded the gallbladder volume." (PMID 39040469, 2024). "Although the evidence is limited and more research is needed, there is also evidence that FGF21 analogs may potentially reduce liver fibrosis, and others are being evaluated to assess their efficacy, safety, and tolerability in patients with cirrhosis." (PMID 39409124, 2024). "NaB alleviated BDL-induced liver fibrosis in the WT mice but aggravated the same in FGF21 KO mice." (PMID 39040469, 2024). "In NAFLD patients, serum levels of chemokines CCL2 was associated with inflammation and advanced hepatic fibrosis, FGF21 was associated with inflammation;In murine models of NASH, CCR2/5 inhibition reduced circulating Ly6C(hi) MoMFs, and the FGF21 agonist reduced body weight, hepatic triglycerides." (PMID 36875101, 2023). "However, as in the pathogenesis of steatohepatitis and liver fibrosis different pathways are dysregulated, combination therapy with an FGF21 analog along with inflammatory pathway inhibition are of interest." (PMID 37189422, 2023). "Thus, we suspect that age‐dependent defects of SIRT1 accelerate the development of liver fibrosis via a mechanism involving altered FGF21." (PMID 36999514, 2023). "In addition, administration of analogues of FGF21 can alleviate liver fibrosis and reduce the phosphorylation level of p38 in liver of NASH mice." (PMID 36742397, 2023). "FGF21 can improve systemic insulin sensitivity and decelerate hepatic fibrosis." (PMID 35269812, 2022). "FGF21 has also shown significant antifibrotic effects in other liver fibrosis models." (PMID 35677107, 2022). "Hence, FGF21 and its analogues have emerged as a potential new therapeutic strategy for liver fibrosis." (PMID 35677107, 2022). "FGF-21 can have implications for viable therapeutic strategies to reduce body weight and increase energy expenditure as well as stop or undo liver fibrosis, inflammation, and fat infiltration by increasing adiponectin secretion to inhibit the nuclear factor κB inflammatory signaling pathway." (PMID 33809508, 2021). "Apart from macrophages, FGF21 could also regulate the activation of hepatic stellate cells which is important during the development of liver fibrosis." (PMID 35035378, 2021). "In the MCD diet-fed animal model of liver fibrosis, metformin or fibroblast growth factor-21 treatment attenuated liver fibrosis by inhibiting succinate and GPR91 signaling, further suggesting the succinate-GPR91 complex as a therapeutic target of liver fibrosis." (PMID 30186230, 2018). "In this study, we tested whether LY2405319, an FGF21 analogue, can be a potential therapeutic treatment for hepatic fibrosis by inhibiting HSC activation via suppressing succinate-GPR91 signaling in an MCD diet -induced mouse model of liver fibrosis." (PMID 29444136, 2018). "The effects of FGF15/19 and FGF21 on hepatic fibrosis are now emerging." (PMID 27699175, 2016). "Preclinical studies with FGF21 analogs have shown promising effects, including inhibition of inflammation and immune cell infiltration in the liver, reduction in liver injury and hepatocyte death, significant improvement in liver fibrosis, and prevention of NASH/MASH development." (PMID 39409124, 2024).
liver fibrosis (continued). "Therefore, the combination of a GLP-1RA and an FGF-21 analog in the same molecule seems to be an appealing approach; however, further studies in different animal models are required to achieve more secure results and, importantly, to elucidate the effect of GLP-1RA/FGF-21 analog on hepatic fibrosis." (PMID 38472647, 2024). "Serum FGF21 is markedly decreased in response to exercise training, offering a novel mechanism to explain the observed reduction in liver fat, improvement in serum biomarkers of liver fibrosis, and gains in cardiorespiratory fitness in patients with NASH who do exercise." (PMID 36986211, 2023). "Therefore, we speculate that FGF21 protects against early liver fibrosis likely through preventing the accumulation of CD36hi/CD9hi KCs, thereby inhibiting activation of hepatic stellate cells to produce collagen." (PMID 36648330, 2023). "Therefore, α‐LA and LTF secreted by FGF21_ADSCs might contribute in part to the potent inhibitory effect of these cells on liver fibrosis in our model." (PMID 30019838, 2018). "Finally, FGF21 gene transfer to the liver reversed hepatic fibrosis." (PMID 29987000, 2018). "In summary, FGF21/sTGFBR2 reduced liver weights, hepatic TAG amount, and liver fibrosis in lipodystrophic mice housed at 30°C." (PMID 40663389, 2025). "Research has shown that the administration of fibroblast growth factor 21 (FGF21) can inhibit protein expressions of collagen I and α-SMA to alleviate liver fibrosis." (PMID 40221799, 2025). "Treatment with Efruxifermin over 24 weeks, a Fibroblast growth factor 21 (FGF21) analogue, improved liver fibrosis at least one stage in patients with F2 or F3 fibrosis." (PMID 40301996, 2025). "shHsd17b13 decreased elevated serum alanine aminotransferase (ALT), serum fibroblast growth factor 21 (FGF21) levels, and markers of liver fibrosis, for example, expression of Timp2." (PMID 40016916, 2025). "Pegozafermin, a long-acting glycol-pegylated recombinant FGF21 analogue, effectively reduces liver fat and fibrosis in patients with severe hypertriglyceridemia, MASH, and liver fibrosis." (PMID 40243151, 2025). "The beneficial effects of fibroblast growth factor 21 (FGF21) and sodium butyrate (NaB) on protection against cholestasis-induced liver fibrosis are not well known." (PMID 39040469, 2024). "Owing to the protective effects of FGF21 on cholestasis-induced liver fibrosis, we further analyzed the beneficial effects of NaB, a well-known gut-microbiota-derived SCFA, to induce FGF21 expression in the liver through activation of PPARα." (PMID 39040469, 2024). "This study aimed to explore the effects of FGF21 and NaB on bile duct ligation (BDL)-induced liver fibrosis." (PMID 39040469, 2024). "In contrast, fibroblast growth factor 21 (FGF21) inhibits HSC activation by blocking the NF-κB pathway, slowing the course of liver fibrosis." (PMID 39359922, 2024). "Specifically, the mitigation of liver fibrosis post-HCV eradication is expected to lead to improvements in liver function, such as enhanced albumin and FGF-21 production." (PMID 37999215, 2023). "It is demonstrated that both low and high doses of FGF21 treatment, in the CCl4-induced model, notably downregulated the mRNA levels of α-SMA and collagen to slow down the process of liver fibrosis." (PMID 35677107, 2022). "We established FGF21‐secreting adipose derived stem cells (FGF21_ADSCs) to enhance the effects of ADSCs and transplanted them into thioacetamide (TAA)‐induced liver fibrosis mice via the tail vein." (PMID 30019838, 2018). "In the phase 2 ENLIVEN trial, pegozafermin (an FGF21 analogue) significantly improved liver fibrosis without worsening MASH in biopsy-confirmed cases, supporting its progression to phase 3 trials." (PMID 40869400, 2025). "In addition, a phase 2b controlled trial is currently underway for the use of Pegasofermin—FGF-21 recombinant analogue for patients with histo-pathologically confirmed non-alcoholic steatohepatitis (NASH) and liver fibrosis." (PMID 40648894, 2025).
liver fibrosis (continued). "Moreover, treatment with LY2405319, an engineered FGF21 analogue, significantly decreases MASH scores, serum liver fibrosis markers, injury markers, and pro-inflammatory markers in mice with MASH." (PMID 40243151, 2025). "While FGF-21 overexpression protects hepatocytes from being damaged in mitochondria-driven oxidative processes, the lack of FGF-21 induces iron-overloaded ferroptosis, driving hepatic fibrosis." (PMID 39411175, 2024). "As liver fibrosis advances, the mRNA level of FGF21 gradually increases, and Interleukin (IL)-1β, through the NF-κB and JNK pathways, gradually enhances the expression of FGF21, thereby inhibiting liver fibrosis." (PMID 39267721, 2024). "It was also revealed that more than 3 months of supplementation with fish oils containing omega-3 PUFA resulted in alkaline phosphatase (ALP), liver fibrosis, alanine aminotransferase (ALT), triglyceride (TG) and fibroblast growth factor 21 (FGF21) reductions and adiponectin increase." (PMID 36902639, 2023). "Animal model evidence is also available, as the lack of FGF21 was found to accelerate the transition from hepatic fibrosis to hepatocellular carcinoma in mice fed with a fat-rich diet." (PMID 32570721, 2020). "Similarly, in a study involving diabetic type 2 patients, serum levels of both FGF-21 and CK-18 were not evidently associated with the presence of NAFLD or liver fibrosis." (PMID 37189422, 2023). "Here, we demonstrate that in the MDR2-KO mouse model of chronic liver inflammation that culminates into hepatocarcinogenesis that FGF21 is expressed in hepatocytes and FGF2 is specifically expressed in stellate cells which may indicate its role in liver fibrosis in chronic liver inflammation." (PMID 37770545, 2023). "However, no significance was found between FGF21 and serum markers for liver fibrosis such as procollagen III n-terminal propeptide (P3NP), laminin, collagen type IV and hyaluronic acid in cirrhotic patients." (PMID 29184085, 2017). "Considering that FGF-21 did not directly affect ChREBP transactivity in rat hepatocytes, probably the effect of FGf21 gene deletion on fructose induced hepatic fibrosis might be due to indirect pathway." (PMID 28241431, 2017). "However, the FGF21 -succinate -GPR91 signaling pathway will likely play a key role in mouse models of liver fibrosis, although it may not be exactly the same in humans, and will require further study to delineate how FGF21 and GPR91 signaling pathway may work in liver fibrosis in humans." (PMID 29444136, 2018). "Although we could not clarify the true outcome of liraglutide on liver fibrosis, it was reported that GLP-1 analogue directly inhibited fibroblast growth factor 21 which promoted the progression of liver fibrosis in mice model." (PMID 22927782, 2012).
cardiac hypertrophy (60 papers, 2011 to 2026). "Consistently, FGF21 cardiac-specific overexpression reversed the cardiac hypertrophy and fibrosis caused by FGF21 deficiency." (PMID 37156793, 2023). "Pre-clinical studies have shown that FGF21 is implicated in the physiopathology of HF (oxidative stress, cardiac hypertrophy, and inflammation of cardiomyocytes)." (PMID 37298029, 2023). "Multiple studies have shown that cardiac production of FGF21 is up-regulated during cardiac hypertrophy, and is associated with the induction of anti-oxidant gene expression in cardiac hypertrophy and heart failure." (PMID 33073318, 2021). "The inhibitory action of FGF21 on cardiac hypertrophy and inflammation was associated with the induction of PPARγ co-activator-1 α (PGC1α)." (PMID 30671457, 2018). "FGF21 deficiency was also found to induce cardiac hypertrophy by promoting oxidative stress, pro-inflammatory pathways, cardiac fibrosis, and cardiac metabolism impairment." (PMID 30185439, 2018). "In this context, it was shown that the inhibitory action of FGF21 on cardiac hypertrophy and inflammation is associated with the induction of PGC1α." (PMID 26379627, 2015). "Deficiency of FGF21 in the heart was demonstrated to induce of cardiac hypertrophy markers and reduce fatty acid oxidation." (PMID 24938300, 2014). "In addition, while experimental study found FGF21 protects against cardiac hypertrophy related to β-oxidation of fatty acids (FAs) in mice, previous clinical studies found that increased FGF21 level was associated with adverse cardiac alterations." (PMID 35145478, 2021). "Deficiency of FGF21 leads to cardiac hypertrophy and adversely affects the ischemic heart." (PMID 34777697, 2021). "In addition, mice globally deficient in FGF21 exhibit increased rates of cardiac hypertrophy and inflammation with reduced capacity for fat oxidation." (PMID 35046901, 2021). "In addition, FGF21-KO mice were more susceptible than wild-type mice to isoproterenol induced myocardial hypertrophy, which manifested through increased heart mass, ventricular hypertrophy, and cardiac dysfunction." (PMID 30927227, 2019). "FGF21-deficient mice were found to exhibit significant cardiac hypertrophy after isoproterenol infusion, which could be prevented by exogenous administration of FGF2110." (PMID 27650781, 2016). "Understanding whether increased FGF21 is associated with myocardial hypertrophy in CKD requires further study." (PMID 21525989, 2011). "As early as 2013, transgenic mice studies demonstrated that FGF21 KO mice suffered maladaptive cardiac hypertrophy and dilatation in response to isoproterenol challenge and that the maladaptive responses were reversed by treatment with exogenous FGF21." (PMID 40149686, 2025). "Increases in serum FGF21 are observed in coronary artery disease, cardiac hypertrophy, and diabetic cardiomyopathy, often paralleling rises in brain natriuretic peptide (BNP) as part of a compensatory response." (PMID 41464745, 2025). "In the heart, PPARα and Sirt1 regulated FGF21 transcription and conferred protection against cardiac hypertrophy by FGF21-mediated amelioration of oxidative stress and inflammation." (PMID 39766329, 2024). "Animal models have shown that FGF21 mitigates abnormal cellular stress responses, such as oxidative stress, inflammation, and apoptosis, in the heart, while reducing cardiac hypertrophy and fibrosis." (PMID 39770968, 2024). "Preclinical studies have demonstrated that FGF21 has a role in the development of heart failure by mitigating oxidative stress, cardiac hypertrophy, and inflammation in cardiomyocytes." (PMID 38333506, 2024). "In mice and humans, FGF21 appears cardioprotective, counteracting for example cardiac hypertrophy and diabetic cardiomyopathy disease." (PMID 39060446, 2024).
cardiac hypertrophy (continued). "A study using angiopoietin 2-induced cardiac hypertrophy mice noted that FGF21 treatment increased SIRT1 deacetylation activity, promoted AMPK phosphorylation, and reduced cardiac hypertrophy in a SIRT1-dependent pathway." (PMID 37416922, 2023). "Previous studies have found cardioprotective effects of FGF21 from cardiac hypertrophy and in a mouse model of experimental myocardial infarction." (PMID 37156793, 2023). "By using an efficient carrier, FGF21 administration attenuated cardiac fibrosis, resulting in decreased mRNA levels of cardiac hypertrophy and fibrosis markers in diabetic cardiomyopathy mice." (PMID 37416922, 2023). "Preclinical research has shown that FGF21 is involved in the pathophysiology of HF through the prevention of oxidative stress, cardiac hypertrophy, and inflammation in cardiomyocytes." (PMID 36028609, 2023). "Endogenous FGF21 protects against cardiac hypertrophy via the sirtuin 1 (SIRT1)–peroxisome proliferator-activated receptor α (PPAR-α) pathway." (PMID 36926038, 2023). "In this way, FGF21 protects against heart disease injuries such as cardiac hypertrophy and infarction." (PMID 36594101, 2023). "Apart from improving cardiac hypertrophy, FGF21 can attenuate cardiac derangements to inhibit cardiac remodeling and HF." (PMID 36594101, 2023). "Taken together, overexpression of exogenous FGF21 in mice appeared to induce a relative concentric cardiac hypertrophy, although the decreased body weight of the transgenic mice precluded definitive conclusions about the cardiac phenotype." (PMID 35513431, 2022). "The genetic ob/ob mouse model lacking leptin is grossly obese and develops elevated blood glucose and FGF21 levels, while exhibiting cardiac hypertrophy at six months of age46." (PMID 35513431, 2022). "Relative cardiac hypertrophy in FGF21-Tg mice was confirmed by gravimetric measurement of heart weight to body weight ratio." (PMID 35513431, 2022). "Preclinical Studies in vivo demonstrated the involvement of FGF21 in the pathophysiologic mechanism of heart failure via protection against cardiac hypertrophy, oxidative stress, and inflammation in cardiomyocytes." (PMID 36618930, 2022). "FGF21 is abundantly secreted by cardiac cells in response to cardiac stress, including cardiac hypertrophy, myocardial ischemia, heart failure, and diabetic cardiomyopathy." (PMID 34630093, 2021). "FGF21 treatment has been shown to be protective against oxidative stress in cultured cardiomyocytes, and against cardiac hypertrophy and myocardial infarction in mice." (PMID 35046901, 2021). "Increasing animal-based studies have showed that elevated FGF21 expression protects type 1 and type 2 diabetic mice from high glucose-induced renal injury and myocardial hypertrophy." (PMID 34773993, 2021). "In a failing heart, FGF-21 exerts protective effects, preventing the development of cardiac hypertrophy and ischemic injury via the Sirt1 (sirtuin-1) pathway." (PMID 33520013, 2021). "Recently, pharmacologic studies have suggested that FGF21 improves cardiac function and alleviates Ang II-induced cardiac hypertrophy in a SIRT1-dependent manner." (PMID 32210821, 2020). "Mitochondrial uncoupling protein 3 (UCP3) exerts an anti-OS function by activating FGF21 under myocardial hypertrophy condition." (PMID 31498116, 2019). "Different cardiac stress stimuli, such as cardiac hypertrophy, transverse aortic constriction, and myocardial infarction, induced expression of FGF21 mRNA in the mouse heart." (PMID 30671457, 2018). "For instance, cold-activated BAT secreted fibroblast growth factor-21 (FGF-21) to recover metabolic lipid and glucose equilibrium and leading to cardio-protection in experimental cardiac hypertrophy and ischemia." (PMID 28376896, 2017). "That study also showed that FGF21 was expressed and secreted by cardiac cells in response to cardiac hypertrophy, myocardial ischemia, and infarction." (PMID 28582462, 2017).